CD4 (CD4 molecule)
Diseases named in the same sentence as CD4 in open-access papers (continued):
Sharing a sentence is not in itself a finding about the gene and the disease.
tumor (continued). "Compared with IgG, toripalimab significantly increased tumor‐infiltrating CD4+ and CD8+ T cells and inhibited tumor cell proliferation, as indicated by the downregulation of Ki67 expression, while the RBPJL‐overexpressing group showed more infiltration in the presence of toripalimab." (PMID 32994998, 2020). "Furthermore, recent studies have shown that multifunctional CD4+ T cells with cytotoxic activity (CD4+ CTL) play essential roles in anti-tumor immunity." (PMID 32486094, 2020). "Furthermore, ICD-induced immune reactions revealed enhanced cytotoxic T lymphocyte (CTL) infiltration, including CD8+ and CD4+ cells, into the tumor site." (PMID 33505987, 2020). "As the most important component of the immune response in the tumor microenvironment of most solid tumors, tumor-infiltrating lymphocytes (TILs), represented by CD4+ Th, CD8+ CTLs, and CD4+/CD25+/FoxP3+ T reg, are only present in remarkably low numbers in the CNS compared to other tumor types." (PMID 33329549, 2020). "Testing combinations of various cytokines in T cell culture media revealed that tumor antigen specific CD4+ T cell growth was improved by culturing in IL-1β, IL-2, IL-6, IL-7, IL-15, IL-21, IL-23, and TGFβ, and that the addition of TGFβ was critical for the improved performance of the cocktail." (PMID 33362774, 2020). "Notably, Th2 cells are the major population of CD4+ T cells within PDAC tumours, and the Th2 CD4+ T cell number is higher than not only the Th1 CD4+ T cell number but also the FoxP3+ Treg cell number." (PMID 32061257, 2020). "In addition, the ectopically expressed membrane-bound form of IL-9 (MB-IL-9) has immune rejection and toxic effects on CT26 tumor cells and can magnify the cytotoxic effects of CD4+ T cells and CD8+ T cells." (PMID 32228589, 2020). "For example, PRG4 may contribute to restrain antitumor CD4+ or CD8+ T lymphocytes within the tumor by binding to CD44 expressed on these cells." (PMID 33199679, 2020). "Moreover, CD80 expression on naive, pre-activated T cells was induced upon co-culture with tumor-associated myeloid cells and levels of CD80 positive CD4 T cells after co-culture with tumor-associated myeloid cells was comparable to levels on CD4 TILs." (PMID 32071302, 2020). "EVs from an antigen-loaded DC bearing tumor antigens that may promote CD4+ and CD8+ T cell responses by direct antigen presentation, which leads to tumor growth suppression with increased efficiency in the case of mature DC-derived EVs." (PMID 33260499, 2020). "Currently, the ability of CD4 expression to predict tumor prognosis is controversial." (PMID 32767974, 2020). "M0 macrophage and neutrophil cells were found to predominate in HCV+ tumor, and resting memory CD4+ T cells, activated memory CD4+ T cells, activated NK cells, resting dendritic cells, and resting mast cells were significantly higher in HBV+ tumor tissue contrast with non-tumor samples." (PMID 32547550, 2020). "Associated with its better antitumor activity, TRIMELVax induced a higher tumor infiltration of CD3+, CD4+ and CD8+ cells than anti-PD-1 monotherapy, while TRIMELVax/anti-PD-1 combination generated higher tumor infiltration of CD4+ cells than each treatment alone." (PMID 32690772, 2020). "Four of 10 assessable patients experienced increases in tumor infiltrating CD4+ and CD8+ cells." (PMID 33178203, 2020). "The low CD4+/CD8+ ratio in tumor‐infiltrating lymphocytes could be an indicator that tumor progression has been prevented." (PMID 32021954, 2020). "STK11 gene inactivation either by mutational or non-mutational machinery is linked to an indolent immune microenvironment with lower Tumor-infiltrating lymphocyte (TILs; CD3+, CD4+, and CD8+ cells) and PD-L1 expression in spite of the existence of moderate to high TMB." (PMID 33194652, 2020).
tumor (continued). "Furthermore, we also found an increase in the total number of CD4+CD127lowIL-10+ T cells as well as an increase in CD4+CD127lowFOXP3+IL-10+ and CD4+CD127lowFOXP3−IL-10+ T cells in the tumor compared to healthy controls." (PMID 32100077, 2020). "Inhibition of PD-L1, LAG3, and CTLA4 could increase CD8 T cells and CD4 T cells and reduce Tregs, thereby enhancing anti-tumor response." (PMID 33401247, 2020). "Given that CD4+ T cells isolated from tumor tissue were enriched for Tregs, we hypothesized that the ratio of Tregs to Th in tumors would correlate with the capacity of the resultant DCs to induce FoxP3+ Tregs." (PMID 32973804, 2020). "CD4+ T cells may be involved in the recognition of tumor antigens, and the activation of M1 macrophages may mediate the inhibition of tumor growth." (PMID 33006365, 2020). "Depending on phenotype, CD4+ T cells can drive or suppress tumour responses." (PMID 32451467, 2020). "Since many tumors can express PD-L1/CD274, the rationale of the PD-L1 pathway blockade is to inhibit the immunosuppressive PD-L1/PD1 interaction between tumor cells and T cells that hampers the activity of CD4+ and CD8+ T cells thereby enhancing T cell-mediated antitumor activities." (PMID 33066260, 2020). "Knowledge about CD4+ T lymphocytes role in tumor immunotherapy is limited and mainly unexplored, and may include enhancement of cytotoxic T lymphocyte responses, licensing of APC, or direct cytotoxic function." (PMID 32582212, 2020). "YYWY could promote the maturity of DCs as well as the responses of CD4+/CD8+ T cell in the tumor tissue." (PMID 32595493, 2020). "Furthermore, a molecular characterization of the cellular content in these tumours showed a majority (70%) of double positive CD4+ CD8+ T-cell tumours, consistent with the reported T-ALL predisposition." (PMID 32060399, 2020). "Interestingly, regulatory T cells (Tregs) inhibit tumor-responsive activated CD4+ T cells by inhibiting cDC2, and Tregs also inhibit mature DCs and prevent their migration to draining lymph nodes." (PMID 33488618, 2020). "It has furthermore been demonstrated that an efficient checkpoint inhibitor-induced antitumor response requires the expression of MHC class II-restricted antigens by tumor cells, combined with a local activation of CD4+ T cells to recruit and activate CD8+ T cells." (PMID 33036244, 2020). "Taken together, an increased anti-tumor immune response by CD4+ T cells and macrophages could be seen for RRAP-mutant tumors." (PMID 33288739, 2020). "Thus, hetIL-15 treatment led to a significant accumulation of GzmB+ CD8+, CD4+ T and NK cells per tumor." (PMID 32461349, 2020). "In both models, prophylactic vaccination using the KP-LC VIReST regime resulted in a heavier infiltration of both CD8+ and CD4+ T cells, demonstrating that vaccination can induce adaptive immune responses capable of homing to the site of tumor development to impede growth." (PMID 32903551, 2020). "However, a recent report pointed out that in NAFLD, the intrahepatic tumor-suppressive CD4+ T cells were selectively damaged, leading to the disorder of lipid metabolism." (PMID 32802885, 2020). "In addition, tumours taken from female mice had significantly more IL-4 + CD4 + T cells, also correlated with increased survival." (PMID 32451467, 2020). "The insufficient number of CD4+ T cells in the tumor microenvironment might be due to the decrease of either T cell infiltration or polarization of CD4+ cells." (PMID 33194642, 2020). "Moreover, immunosuppressive tumor-associated macrophages (TAMs) and tumor-associated neutrophils (TANs) impair CD8+ cytotoxic T lymphocytes (CTLs), while promoting accumulation and activation of CD4+CD25+Tregs." (PMID 33020428, 2020). "In the current study, Doxil® reduced the number of Tregs, TAMs and MDSCs from tumor tissue of immunocompetent mice and Doxil® skewed polarization from M2 to M1 phenotype, which would lead to an increase in CD4+/CD8+ T cell-mediated antitumor immunity." (PMID 33086690, 2020).
tumor (continued). "To explore whether targeting USP7 can activate systemic adaptive anti-tumor immunity, we examined the population of CD4+T cells, CD8+T cells, Th1 cells, and CTLs in the spleen." (PMID 32802195, 2020). "Importantly, the ratio of CD8+ TILs over CD4+ TILs significantly increased after αPD1 treatment in both tumor models." (PMID 32690667, 2020). "The CD4 helper (Th) 1 subset is the most prominent for anti-tumor immunity." (PMID 33329566, 2020). "Additionally, TLR8 signaling can reverse the suppressive functions of human tumor-derived CD4+ T cells, CD8+ T cells, and γδ T cells, which resulted in enhanced anti-tumor immunity." (PMID 33102225, 2020). "Furthermore, TMZ treatment was able to increase cross-priming of tumor antigen-specific CD4+ T cells and CD8+ T cells and suppressed the frequency of regulatory T cells (Tregs)." (PMID 33374542, 2020). "Moreover, Yanmei and colleagues identified induced CD69+CD4+CD25− T cell population along with tumour progression in an orthotopic hepatic tumour mouse model." (PMID 31907005, 2020). "Thus, it was concluded that VISTA selectively suppresses CD4+ T cell-mediated tumor immunity in this mouse glioma model." (PMID 32600443, 2020). "The biological activity of ANGPT2 is not only restricted to neoangiogenesis but can also impact the macrophage phenotype by promoting PD-L1 expression and IL-10 secretion, which, in turn, are involved in the expansion of CD4+CD25highFoxp3+ Tregs in tumor-bearing mice." (PMID 33168050, 2020). "Similarly, dual-targeted CAR-T cells -CD4+ T cells secreted higher levels of IL-2 in the co-cultures of PD-L1+ tumor cells (e.g. A549, NCI-H292, SKOV3) than that in the co-cultures of HER2+ tumor cells." (PMID 33292688, 2020). "Follicular helper CD4+ T cells perform a central role in initiating and activating immune responses against tumor and helping CD8+ T cells function, which may be a reason why it is relatively high in the low-risk immune group." (PMID 32133292, 2020). "In this regard, as early as 5 days following 17D intratumoral treatment regimens, the absolute number of CD8 T cells per gram of tumor was increased, while CD4+FOXP3+ Tregs were markedly reduced in their numbers, resulting in high CD8/Treg and conventional CD4 T (Tconv)/Treg ratios." (PMID 31746149, 2020). "Therefore, we estimated the relationship between the abundance of six types of tumor-infiltrating immune cells (B cells, CD4+ T cells, CD8+ T cells, neutrophils, macrophages, and dendritic cells) and the signature risk score in MIBC." (PMID 33456631, 2020). "Additionally, a recent scRNA-seq study on bladder cancer identified two cytotoxic CD4+ TH subsets that were clonally expanded and capable of killing analogous tumor cells in an MHC-II-dependent manner." (PMID 33329692, 2020). "Furthermore, in the suppressive TME, migratory cDC2s, which are essential for the priming of CD4+ T cells, are reportedly suppressed by Tregs, resulting in suboptimal priming of CD4+ helper T cells in the tumor-draining lymph node." (PMID 33123174, 2020). "Interestingly, we also found that uLUAD patients have a higher level of CD8+ and CD4+ T cells in the tumor milieu." (PMID 32850350, 2020). "In particular, combinatorial therapeutic approaches that re-educate the TME by limiting the accumulation of immunosuppressive immune cells, such as Foxp3 regulatory T cells (Tregs) and tumor-associated macrophages (TAMs), while promoting CD8+ and CD4+ effector T cell activity is critical." (PMID 32849557, 2020). "In the B16 sonicated tumors, significant increases in TUNEL staining and the localization of tumor-infiltrating CD4+ and CD8+ T-cells was detected on day 2; however, there were relatively few differences in immune cell populations in the tumors, Sp, and LNs compared to controls." (PMID 32033171, 2020). "Similarly the infiltration of cellular sources of IL-22 including Th22 and CD4+ T cells in the intratumoral tissue increases, corresponding to the stage of tumor." (PMID 33042126, 2020).
tumor (continued). "So, upregulation of CD4 + PD-1lowTIM-3+ in the tumour microenvironment also could potentially become an important predictive factor along with CD8+ PD-1highTIM-3+ cells." (PMID 32277125, 2020). "Further evidences of radiation-induced immune responses were reported by both pre-clinical and clinical studies where heightened activation and recruitment of anti-tumor immune subsets such as CD4+, CD8+ T cells, cytotoxic NK, and CD8+CD56+ natural killer T (NKT) cells to the TME were observed." (PMID 33117354, 2020). "Our adoptive cell transfer experiments sought to confirm that G-CSFR−/− CD4+ cells, which were prevalent in anti-tumor phenotypes, could transfer those properties to the tumor microenvironment of Rag2−/− mice, which lack T cells." (PMID 33042110, 2020). "Interestingly, it was found that CIITA-tumor tissue was rapidly infiltrated by CD4+ T cells already at day 4 after tumor cell injection." (PMID 33138029, 2020). "Moreover, in an IL-22-free environment mice receiving Il22−/− or Tg × Il22−/− CD4+ T cell showed an equal tumor load, indicating that the observed effect is IL-22 dependent." (PMID 32451418, 2020). "TAMs can also directly inhibit anti-tumour cytotoxic T-cell proliferation and promote regulatory CD4+ T-cell expansion via surface expression of PD-L1, secretion of IL-10 and TGF-β and through the production of nitric oxide and arginase in the same manner as MDSCs." (PMID 32157213, 2020). "In addition, multiple tumor cell injections in the mouse liver metastasis models were found to increase the number of CD4+ CD25 + Treg cells and the expression of cytokines IL-10 and TGFβ-1." (PMID 32408477, 2020). "Notably, TIGIT is highly expressed in CD8+T cells, CD4+T cells, and NK cells during tumor infiltration." (PMID 33490104, 2020). "These immunosuppressive cells are already present in preneoplastic lesions (PanINs), indicating that they may be key players in tumor initiation and progression by blocking the antitumoral activity of effector CD4+ and CD8+ T cells." (PMID 32823814, 2020). "In studies comparing the immune-phenotype of ZAP-70 positive and ZAP-70 negative CLL patients, tumor ZAP-70 expression was associated with increased CD4 central memory T cells and CD3/CD69+ T cells with decreased CD4/CD8 ratio in the peripheral blood." (PMID 33194762, 2020). "How to reconcile the apparent dichotomy of CD4+ T cells being necessary to trigger and maintain the in vivo immune response against the tumor and yet being almost dispensable in vaccinated immune mice to reject a challenge with parental tumor cells?" (PMID 33138029, 2020). "However, treatment significantly reduced activated Tregs in the tumor microenvironment: Foxp3+CTLA4+ CD4+ Tregs were reduced in all patients, from 11.8% to 2.9%, p = 0.0067." (PMID 32681091, 2020). "MHC class II-restricted CD4+ T cells are able to induce more robust and broader anti-tumor immune responses which could improve outcomes in cancer immunotherapy." (PMID 31915853, 2020). "Moreover, DCK expression was positively correlated with TIICs, including CD4+ and CD8+ T cells, B cells, monocytes, tumor-associated macrophages (TAMs), M1 and M2 macrophages, neutrophils, natural killer cells, and dendritic cells." (PMID 32690026, 2020). "In line with this notion, analysis of FOXP3+ CD4+ T cell frequencies across the tissues of MC38 tumor‐bearing wild‐type and Usp44fl/flFoxp3Cre+ mice revealed marked reductions in the relative size of the Treg pool when USP44 expression was lacking in these cells." (PMID 32644293, 2020). "A small number of CD4 positive cells could be observed infiltrating the tumor mass in all samples, as well as in adjacent brain tissue." (PMID 32469935, 2020). "Moreover, in a recent study including NSCLC and RCC patients treated with nivolumab and pembrolizumab, authors also highlighted the relevance of central memory CD4 T cells for tumor immunity." (PMID 32244396, 2020).
tumor (continued). "T cells CD8 (31 tumor types versus 32 tumor types), T cells CD4 memory activated (26 tumor types versus 26 tumor types), Macrophages M1 (26 tumor types versus 23 tumor types), Macrophages M0 (23 tumor types versus 20 tumor types) turned to be the consistent TILs pattern of inter-group differences." (PMID 33585244, 2020). "The role of CD4+ T cells is increasingly being studied in the T-cell response against tumours." (PMID 32433601, 2020). "There are also several reports describing recognition of tumor antigens by human CD4+ T cells." (PMID 32508825, 2020). "Moreover, tumor cells treated with SK and lipopolysaccharide (LPS) activate DCs and induce the differentiation of tumor-specific Th1 and Th17 CD4 T cells." (PMID 32656498, 2020). "Moreover, CD8+ and CD4+ T cells which do infiltrate the tumour seem unable to mount an anti‐tumour effector response in GBM." (PMID 32567735, 2020). "However, clonal T cells in cytotoxic, exhausted, and Treg cells shared limited TCR between the tumor and adjacent tissues, which suggested potential common origins of some Tregs and naïve CD4 T cells." (PMID 33293583, 2020). "Memory (22.6%) and naïve (16.1%) B cells were the most abundant immune infiltrates in DLBCL, followed by tumor-related macrophages (M0 11.7%, M2 8.2%, and M1 7.4%), CD4+ (10.3%) and CD8+ (8.2%) T cells, resting (2.3%) and activated (0.6%) NK cells, and Tregs (1.4%)." (PMID 32844062, 2020). "Furthermore, multiple cytokine expression would be an interesting future direction to explore in an in vivo tumor model comparing CD4+ T-cell infiltration." (PMID 33292267, 2020). "Unfortunately, a large number of PDAC tumours demonstrate increased infiltration of T regulatory cells, myeloid-derived suppressor cells (MDSCs) and M2-like macrophages, blocking the activities of CD4+ and CD8+ T cells." (PMID 32635552, 2020). "Peptide- or protein-loaded dexosomes could hinder tumor growth by recruiting CD4+ and CD8+ T and B cells in vivo." (PMID 33228747, 2020). "In addition, the ratios of CD4 + Teff/ CD4 + Treg and CD8 + T/Treg in corresponding immune tissue were also associated with statistically significant differences alongside tumor growth in different animal models." (PMID 32805718, 2020). "This suggests a key role for CD4+ T cells in the neo-antigen directed anti-tumor immune response." (PMID 33353155, 2020). "Additionally, HSF significantly decreased the CD4+CD25+CD127- population (regulatory T cells) in the tumor environment." (PMID 33488388, 2020). "Furthermore, Tumor-infiltrating CD4+ T lymphocytes induce apoptosis by activating CD8+ T lymphocytes and releasing cytotoxic factors." (PMID 33120809, 2020). "The decrease in CD4+ T-helper lymphocytes may result in a suboptimal lymphocyte-mediated immune response to tumor cells." (PMID 32731872, 2020). "In multivariate analysis along with other clinical items including tumour stage, only tumour grade significantly correlated with higher dysfunctional populations of both CD4 T and CD8 T cells (odds ratio: 3.48, 95% confidence interval [CI]: 1.39–8.73, P = 0.008)." (PMID 32277125, 2020). "CD4+CD25+FoxP3+ cells isolated from patients diagnosed with HCC showed an increased transcriptional activity compared to controls, regardless the pathogenic basis of tumor development." (PMID 32488850, 2020). "Correlation analysis was conducted between the glycolysis risk scores model and cells in the tumor microenvironment using the TIMER2.0 database, finding that the number of macrophages, myeloid dendritic cells, and resting CD4+ memory T-cells changed significantly with differences in risk score." (PMID 32744303, 2020). "However, CD4 CAR T cells demonstrated comparable effectiveness in directly killing target tumor cells both in vitro and in vivo." (PMID 33292660, 2020).